HSPA9 (heat shock protein family A (Hsp70) member 9)
Diseases named in the same sentence as HSPA9 in open-access papers (continued):
Sharing a sentence is not in itself a finding about the gene and the disease.
tumor (continued). "Consistent with our results in TCGA, HSPA9 and HSPA8 were significantly upregulated in CRC tissues compared with normal tissues, and mainly localized to the cell membrane and cytoplasm in the tumor cells." (PMID 35711437, 2022). "The overexpression of PSMB6, HSPA9, DUT, CDK7, and PLK1 was seen in resected tumor tissues compared with adjacent normal tissues, while FOLR2 was expressed more in normal tissues." (PMID 34721732, 2021). "In summary we present evidence that miR-525-3p is an important regulator of survival in normal and in tumor-derived cell lines, and that the direct targets ARRB1, HSPA9 and TXN1 each have a direct effect on survival after irradiation." (PMID 24147004, 2013). "The heatmap showed significant differential expression of genes such as HSPA9, CCL19, and CD247 in cluster B, which may implicate their roles in tumor progression." (PMID 38312844, 2024). "Therefore, HSPA9 and HSPD1 can also be further analyzed as the core genes for the study of tumor–endothelium interaction." (PMID 33681194, 2021). "Moreover, heat shock proteins (HSPs) including HSPA8, HSPA9, and HSPD1 in tumor tissues displayed aberrant lysine acetylation modification." (PMID 33093847, 2020).
infection (24 papers, 2013 to 2026). The state of being infected such as from the introduction of a foreign agent such as serum, vaccine, antigenic substance or organism. "Notably, GRIA1, a regulator in glutamatergic signaling, and HSPA9, a stress-associated protein, were detected only in EVs from infected macrophages, suggesting specific roles in intercellular communication during infection." (PMID 33785616, 2021). "HSPA9 plays a crucial role in the viral life cycle, including viral entry, translation during infection, and the assembly of viral particles." (PMID 40425856, 2025). "For example, the HSP70 isoforms HSPA1, HSPA8, and HSPA9 are required for viral entry and the translational steps of the infection." (PMID 32760390, 2020). "Other host proteins that were not recurring across the 15 interactomes but common in other interactomes such as HYOU1, PDIA3, HSPA9, CTSS, etc., have been already also found deregulated upon pathogenic infection." (PMID 30815000, 2019). "This fluctuation contrasts with certain HSP70 isoforms, where several are upregulated (e.g., HSPA1L, HSPA2, HSPA5, HSPA9, HSPA12, and HSPA13), while others from the HSP70 family are downregulated post-peak infection phase (Chand, Iyer & Mitra, 2021)." (PMID 39308823, 2024). "We found that, upon infection with S. aureus, ACO2 KD further increased the expression of HSPD1, HSPA9, and CLIPP, three of four selected targets of ATF5, a key mediator of the UPRmt and the mammalian ortholog of C. elegans ATFS-1, in HeLa cells." (PMID 37349299, 2023).
neurodegenerative disease (6 papers, 2021 to 2025). A disorder of the central nervous system characterized by gradual and progressive loss of neural tissue and neurologic function. "Mortalin/HSPA9 was identified as a pexophagy regulator and shown to partiallylocalize to peroxisomes, where it has been proposed to suppress the generationof pexophagy-promoting ROS.Reduction of this protein has been linked to neurodegenerative diseases such asParkinson’s and Alzheimer’s." (PMID 39904371, 2025). "As mitochondrial stress-induced ciliogenesis is mediated by mtROS, which activates autophagy, further exploration of the role of HSPA9 in the regulation of primary ciliogenesis will be helpful in understanding neurodegenerative diseases, including PD." (PMID 37170364, 2023). "Significant mitochondrial fragmentation is induced by excessive mtROS production, and we previously reported that the knockdown of HSPA9 increases mitochondrial fission in a neurodegenerative disease model." (PMID 37170364, 2023). "HSPA9 is a heat-uninducible protein of the HSPA family, which plays critical roles in stress response, energy generation, neurodegenerative disease, and carcinogenesis." (PMID 34765552, 2021).
adenocarcinoma (3 papers, 2018 to 2022). A common cancer characterized by the presence of malignant glandular cells. "In a recent retrospective study of 636 RP patients, HSPA9 expression was associated with an increased risk of high-grade adenocarcinoma and biochemical failure after salvage therapy, as detected by microarrays." (PMID 35954429, 2022).
genetic diseases (2 papers, 2021 to 2024). "In 2015, recessive mutations in the mortalin-encoding HSPA9 gene were identified in three children suffering from a genetic disorder named EVEN-PLUS syndrome (epiphyseal, vertebral, ear, nose, plus associated findings)." (PMID 34360841, 2021).
metabolic disorders (1 paper, 2026). "We confirmed that LINC01013 as a protein-binding scaffold connecting HSPA9 and VDAC1, contributing to the oligomerization of VDAC1 and mitochondrial dysfunction including oxidative stress and metabolic disorders, and ultimately hypoxic PH progression." (PMID 41491061, 2026).
HSPA9 also shares sentences with these, for which no sentence is quoted: prostate carcinoma (5 papers); cervical carcinoma (4); diabetes (4); osteosarcoma (4); diabetic retinopathy (3); thymoma (3); type 2 diabetes (3); bacterial infection (2); Breast tumors (2); cardiomyopathy (2); colorectal adenocarcinoma (2); endometrial cancer (2); myocardial infarction (2); myocardial ischemia (2); myositis (2); abscesses (1); adenoma (1); alcoholic liver diseases (1); asthenozoospermia (1); asthma (1); atherosclerosis (1); attic cholesteatoma (1); autoimmune disease (1); bladder cancer (1); bone marrow failure (1); brain cancer (1); brain tumors (1); Cachexia (1); cholesteatoma (1); CODAS syndrome (1).
A further 71 diseases each share a sentence with HSPA9 in 1 paper.